IL1B (interleukin 1 beta)
Diseases named in the same sentence as IL1B in open-access papers (continued):
Sharing a sentence is not in itself a finding about the gene and the disease.
malaria (continued). "In addition, the release of both Plasmodium-derived Hz and merozoites during the erythrocyte burst phase of the disease coincides with the massive induction of pro-inflammatory cytokines, such as IL-1β and TNF, and with the periodic fevers characteristic of malaria." (PMID 19696895, 2009). "The proinflammatory cytokines: TNF‐α (p < .001), IFN‐ɣ (p < .001), IL‐1β (p < .001), IL‐6 (p < .001), GM‐CSF (p < .001), and the anti‐inflammatory cytokine IL‐10 (p < .001) levels were significantly higher in malaria‐infected males and females than in their counterparts without malaria." (PMID 39240033, 2024). "Malaria-naïve adults and children from low-transmission regions tend to generate strong pro-inflammatory responses: TH1 cytokines IFN-γ and TNFα, and other pro-inflammatory cytokines such as IL-1β and IL-6, are produced, which may favor generation of TH1-like responses." (PMID 31156642, 2019). "However, the cluster of cytokines—TGF-β, TNF-α, IL-10, and IL-1β—that differentiated CM from other falciparum malaria manifestations in Gondia could not distinguish severe malaria cases in Odisha." (PMID 26602091, 2015). "Our findings revealed a significant elevation in IL-1β, but not TNF-α, in mice with tumors and treated with chloroquine, in mice infected with Plasmodium berghei, and in mice with tumors and healed of malaria." (PMID 38774541, 2024). "Mice with tumors showed a significant increase in serum levels of IL-1β but not TNF-α when treated with chloroquine, infected with malaria, or healed of malaria." (PMID 38774541, 2024). "The absence of IL-1β and IL-6 and TNFα during CHMI is not unusual as reported in other controlled malaria studies." (PMID 34548530, 2021). "Taken together, these results demonstrate that the macrophage pro-inflammatory response to malaria PAMPs in terms of TNF secretion as well as Tnf and Il1b gene transcription is not as pronounced as that elicited by LPS." (PMID 28560184, 2017). "IL-1β and TNF-α are pyrogens cyclically released by monocytes, macrophages, and neutrophils that participate in universal mechanisms of systemic inflammation and febrile response in infectious and noninfectious diseases, such as malaria and cancer." (PMID 38774541, 2024). "However, levels of TNF‐α,10 IL‐1β,16 IL‐6,8, 33 IFN‐ɣ,33 IL‐10,11, 33 and GM‐CSF27 were not different when malaria‐infected children were compared to their counterparts without the infection in previous studies." (PMID 39240033, 2024). "Whole blood from asymptomatic participants with and without positive malaria microscopy were ex-vivo stimulated with S. aureus, E. coli LPS and Salmonella Typhimurium; cytokine concentrations (TNF-α, IFN-γ, IL-1β, IL-6, IL-10) were measured on supernatants using ELISA." (PMID 34177883, 2021). "Participants with asymptomatic malaria had also lower IFN-γ and IL-10 responses after Salmonella Typhimurium stimulation, while monocyte cytokines (IL-1β, IL-6, TNF-α) were not statistically different between slide negative participants and participants with asymptomatic malaria." (PMID 34177883, 2021). "For malaria infected individuals (M and CI) the profile was high levels of IL-1β, IL-6, TNF-α IL-10, and CRP and decreased levels of IL-17A while for malaria negative individuals (IP and UN) the profile was high levels of IL-17A, NO and decreased levels of IL-10 and CRP." (PMID 25309052, 2014). "The LD between IL1B -31C>T and IL1RA VNTR was not strong in the studied population (for mild malaria patients, P = 0.14 by likelihood ratio test based on a permutation precedure; for cerebral malaria patients, P = 0.50 by likelihood ratio test based on a permutation precedure)." (PMID 16098232, 2005).
multiple sclerosis (130 papers, 2008 to 2025). A progressive autoimmune disorder affecting the central nervous system resulting in demyelination. "NF-κB activation in turn upregulates the expression of several genes implicated in the pathogenesis of multiple sclerosis, such as TNFα, iNos and IL1α/IL1β." (PMID 37999377, 2023). "For example, IL-1β is a driver of multiple sclerosis (MS), and mice deficient in IL-1β are resistant to experimental autoimmune encephalomyelitis (EAE)." (PMID 35293780, 2022). "The dysregulation of tight junctions leads to altered barrier function resulting in changes in levels of inflammatory cytokines such as IFN-α, IFN-γ, IL-6, and IL-1β as seen in inflammation-associated diseases such as multiple sclerosis and cancer." (PMID 35046947, 2021). "Regarding its in vivo functions, NEK7-deficient mice with multiple sclerosis showed less IL-1β-related inflammatory disorders than wild-type mice." (PMID 31787755, 2019). "IL-1β transcript or protein was detected in the cerebrospinal fluid, blood or lesions of patients with multiple sclerosis and was linked to the extent of cortical demyelination or to disease severity." (PMID 29724241, 2018). "The role of the IL-1β has been implicated in a variety of inflammatory and neurodegenerative processes occurring in multiple sclerosis." (PMID 28623311, 2017). "In previous studies, TNFα, IL-1β, and IL-6 have been implicated as mediators of multiple sclerosis pathology." (PMID 23861993, 2013). "Noteworthy, IL-1β has been implicated in perpetuating immune responses and contributing to disease severity in a variety of CNS diseases ranging from diabetic retinopathy, traumatic brain injury, multiple sclerosis, and neurodegeneration." (PMID 38139384, 2023). "Indeed, high concentrations (500 ng/mL) of IL-1β can have neurotoxic effects on neurons when exposed for 3–5 days, and IL-17 is detected at high levels in the CNS in multiple sclerosis and associated with the neuroinflammatory pathology of the disease." (PMID 37919762, 2023). "For example, IL-1B (-511C > T) has been reported to be associated with the severity and progression of multiple sclerosis (MS), while the NLRC4 rs479333 G > C variant has shown beneficial effects by limiting disease progression and supporting response to treatment with INF-β." (PMID 37833739, 2023). "Moreover, compared to wild-type mice, NEK7-deficient mice with multiple sclerosis present with fewer IL-1b-related inflammatory diseases." (PMID 30202244, 2018). "Several studies have shown that increases in interleukin (IL)-1β expression are associated with neurodegeneration, multiple sclerosis, traumatic brain injury and diabetic neuropathy, which may explain the typical hippocampal volume loss seen in depressive patients." (PMID 39056709, 2024). "DMF blocks a final common pathway of inflammasome signalling in vitro, and in keeping with this, DMF treatment normalises serum IL-1β in patients with multiple sclerosis and reduces serum CRP in an animal model of inflammation." (PMID 38296965, 2024). "In contrast, a study by Silvia Rossi and colleagues showed that the IL-1β/IL-1Ra ratio was significantly higher in the cerebrospinal fluid of patients with active multiple sclerosis." (PMID 39000506, 2024). "For instance, stimulation of human brain ECs with TGF-β1 and IL-1β promoted EndMT and increased markers of multiple sclerosis in vitro." (PMID 39000490, 2024). "For example, astrocytes and microglia are demonstrated to secrete abundant Il-1β in models of multiple sclerosis (MS)." (PMID 37443034, 2023). "In multiple sclerosis, caspase-1, IL-18, and IL-1β are positively regulated in PBMCs and in mononuclear cells in the CSF during disease development, and caspase-1 expression is upregulated in demyelinating lesions." (PMID 36298702, 2022). "In patients with multiple sclerosis, a high-level expression of Let7d and positive correlation with IL-1b expression were shown." (PMID 35679898, 2022).
multiple sclerosis (continued). "IL-1β is also a proinflammatory cytokine, and has been of interest in various central nervous system (CNS) diseases, like multiple sclerosis." (PMID 36061386, 2022). "MCC950 reduces IL-1β production in vivo and attenuates the severity of a multiple sclerosis mouse model (experimental autoimmune encephalomyelitis mice)." (PMID 35219323, 2022). "The expression of CLDN4 by astrocytes has only been identified in mouse models of CNS inflammation (acute CNS inflammation model (stereotactic injection of the pro-inflammatory cytokine IL-1β and model of multiple sclerosis: EAE MOG35-55)." (PMID 33253145, 2020). "The spleen, the lymphoid organ and reservoir of myeloid cells, was proved to mobilize neutrophils and inflammatory monocytes/macrophages to the blood when affected by the presence of IL-1β in multiple sclerosis." (PMID 32421725, 2020). "It has been reported that IL‐1β levels increase proportionately with the volume of brain lesions in patients with multiple sclerosis." (PMID 33150666, 2020). "For example, release of astrocyte-derived TIMP-1 in an experimental autoimmune encephalomyelitis (EAE) model of multiple sclerosis has a protective effect and results in myelin sparing and attenuates the effect of IL-1β on the wound healing responses in vitro." (PMID 31616247, 2019). "MiR-455-5p is negatively correlated with the activation of the NF-κB pathway, thus inhibiting the expression of IL-1β, IL-6 and IL-8 and in turn ameliorating the severity of multiple sclerosis." (PMID 31304055, 2019). "Activation of the NOD-like receptor protein 3 (NLRP3) inflammasome is involved in the maturation and secretion of IL-1β and IL-18 and, thus, plays a key role in the pathogenesis of many inflammatory conditions, including multiple sclerosis (MS)." (PMID 31736980, 2019). "In a multiple sclerosis model producing OL death, IL-1β -/- mice expressed OPCs up to six weeks after chemical depilation, also indicating that IL-1β elimination did not influence OPC proliferation." (PMID 29690837, 2018). "It revealed that sildenafil can decrease the levels of TNF-α, interferon (IFN)-γ, IL-2 and IL-1β in animal model of multiple sclerosis." (PMID 28210757, 2017). "LPS stimulation upregulates the expression of the inflammasome related genes, NLRP3, Caspase-1, and IL-1β in PBMC from multiple sclerosis compared to healthy controls." (PMID 27795729, 2016). "Interleukin (IL)-1β is a pro-inflammatory cytokine that plays a role in the pathogenesis of multiple sclerosis (MS) and experimental autoimmune encephalomyelitis (EAE), the animal model for MS." (PMID 27266875, 2016). "In contrast infiltration of T cells occurs in multiple sclerosis and PD, and levels of IL-1β, IL-6 and TNF-α are elevated in the cerebrospinal fluid of PD patients." (PMID 26634899, 2015). "IL-1β is increased in CSF in CNS inflammatory disorders where there is manifest acute CNS damage, such as multiple sclerosis (MS)." (PMID 25124807, 2014). "We analyzed the expression of IL-1β in human NMO lesions of different stages in comparison to multiple sclerosis lesions and controls." (PMID 24252536, 2013). "FTY720 (FTY, fingolimod), an Sph analogue derived from a fungal metabolite, and that is approved for the treatment of multiple sclerosis, also induced a significant release of mature IL-1β when used at an equivalent concentration." (PMID 22105559, 2012). "The roles of cytokines, such as IFN-γ, TNF-α, IL-1β and IL-6, expressed in inflammatory diseases such as multiple sclerosis are complex." (PMID 18793322, 2008). "Notably, HIF-1α deficiency in myeloid cells reversed neurological symptoms and reduced IL-1β and IL-17 production in a mouse model of multiple sclerosis with Pg infection." (PMID 40494891, 2025). "However, elevated levels of IL-1β in the CNS, along with subsequent neuroinflammatory processes, have been reported in various neurological disorders, including multiple sclerosis (MS), AD, and PD." (PMID 40076857, 2025).
multiple sclerosis (continued). "Futher, corticosteroid-based treatments show effective anti-inflammatory efficacy as therapeutic agents for infectious diseases of the brains and in mouse model of multiple sclerosis, significantly down-regulating pro-inflammatory cytokines such as IL-1β, IL-6, IL-17, IFN-γ, and TNF-α." (PMID 40390112, 2025). "Elevated levels of IL-1β and IL-6 have also been observed in patients with multiple sclerosis." (PMID 36675141, 2023). "Interestingly, the inflammatory cytokine IL1β was observed to affect BBB permeability by influencing blood vessel plasticity via HIF regulation in the angiogenesis program in multiple sclerosis patients." (PMID 33763387, 2021). "NLRP3 was activated in multiple sclerosis and induced the secretion of IL-1β as well as IL-18." (PMID 31892810, 2019). "Whether this mechanism could play a role in other neurological disorders (multiple sclerosis, neurodegenerative disorders) characterized by high levels of IL-1β and dysfunction of Kir4.1 deserves further investigation." (PMID 23270518, 2012). "In multiple sclerosis, IL-17 was produced by microglia in response to IL-23 or IL-1β." (PMID 21858022, 2011). "Sex differences in the expression of IL1β by astrocytes in vivo could result in sex differences in neuronal injury and in the remyelination of multiple sclerosis lesions." (PMID 21745355, 2011). "IL-1β can activate microglia and astrocytes, leading to the synthesis of proinflammatory and chemotactic mediators, and perpetuate a variety of CNS diseases including multiple sclerosis, neurodegenerative diseases, traumatic brain injury, and diabetic retinopathy." (PMID 41403939, 2025). "Moreover, there is evidence that astrocytes can express all the components of the NLRP3 inflammasome (NLRP3, ASC and caspase-1), and produce IL-1β in various central nervous system diseases, such as multiple sclerosis, neuromyelitis optica, and cerebral infarction." (PMID 37921870, 2023). "Indeed, IL-1β is neurotoxic and exacerbates neurodegenerative pathology and behaviors in multiple disease models, including AD, PD, poly I:C-induced neurodegeneration, and multiple sclerosis." (PMID 29970116, 2018). "Finally, the screening of a large sample of CNS lesions from NMO and multiple sclerosis patients revealed large numbers of interleukin-1 beta-reactive macrophages/activated microglial cells in active NMO lesions but not in MS lesions with comparable lesion activity and location." (PMID 24252536, 2013). "On the other hand, pro-inflammatory cytokines such as IL-6, IL-1β, IL-17, IL-22, TNF-α, IL-12, and IFN-γ are thought to play a pivotal role in the pathogenesis of multiple sclerosis (MS) through various signaling pathways." (PMID 40507498, 2025). "Consistent with existing data, IL-1β suppression, and related anti-inflammatory interventions restore CNP expression and myelin architecture in experimental multiple sclerosis models." (PMID 40500721, 2025). "In Multiple Sclerosis (MS), CBD in preclinical models of MS resulted in a reduction of proinflammatory cytokines such as IL-17A, IFN-γ, TNF-α, IL-6 and IL-1b and an increase in anti-inflammatory cytokines such as IL-4, IL-10 and TGF-β." (PMID 38601151, 2024). "Gli is a hypoglycemic agent that can inhibit NLRP3 mediated production of IL-1β by blocking P2X7 ion-channels; this compound also modulates TRPM4, a cation channel that mediates axonal and neuronal degeneration in Multiple Sclerosis (MS)." (PMID 38139851, 2023). "Multiple sclerosis, a disease treated with IFN-β (among other therapeutic options) and which is also characterized by increased IL-1β expression, will be described." (PMID 34066649, 2021). "A significant reduction of IL-1β by CBD treatment in a murine viral model of multiple sclerosis was also shown, suggesting its role in combating inflammation in multiple sclerosis." (PMID 33584697, 2020).
multiple sclerosis (continued). "Second, we assess the astrocytic response to IL-1β, TNF-α, and IL-6, all cytokines important in neuroinflammation, such as multiple sclerosis." (PMID 30409508, 2018). "In this line of findings, the peripheral upregulation of IL-17 and IL-1β observed in this study could suggest their role in the neurotoxicity reported in autism, supported by an autoimmune mechanism, similar to those reported in other neurodegenerative disorders like multiple sclerosis." (PMID 27983615, 2016). "The aim of this study was to evaluate ENA 78, IL-1β and TNF-α plasma levels in multiple sclerosis (MS) and neuromyelitis optica (NMO) patients." (PMID 27401736, 2016). "The HERV-W syncytin-1 exerted its inflammatory effects by induction of proinflammatory mediators, such as IL-1β, IL-6, IL-12, iNOS, and TNF-α, leading to neuron inflammation in multiple sclerosis patients." (PMID 21772664, 2011). "Pharmacological inhibition of NLRP3 inflammasome activation and IL-1β production with specific antagonists, such as MCC950, has exhibited plausible effects on preventing neurological impairment of multiple sclerosis, neurodegenerative diseases, and traumatic brain injury." (PMID 33676524, 2021). "Likewise, in an animal model of multiple sclerosis, increasing endocannabinoid tone with UCM-707—an AEA uptake inhibitor—resulted in a significant reduction of IL-1β levels and an increase in IL-10 levels." (PMID 34685523, 2021). "The model was also used to dissect the molecular pathogenesis of inflammatory CNS diseases such as multiple sclerosis, by determining the effect on myelin of cytokines such as tumour necrosis factor-α (TNF-α), interleukin-1β (IL-1β), interleukin-6 (IL-6) and interferon-γ (IFN-γ)." (PMID 18793322, 2008). "Before any anti- IL-1β treatment, one patient had white matter lesions with demyelination as it may be seen in multiple sclerosis without any neurological sign (except for chronic headaches) unlike the only other CAPS patient described in literature with demyelinating disease who had a hemiparesia." (PMID 28196516, 2017). "Moreover, other groups also described elevated levels of IL-1β or IL-1β/TNF-α induced molecules like IL-1ra, IL-6, IL-8, IL-13, G-CSF, and Cxcl10 (IP-10) in the CSF of NMO patients, compared to the CSF of patients with multiple sclerosis or other neurological diseases." (PMID 24252536, 2013). "In mice with multiple sclerosis, a lack of CTSZ can significantly reduce the level of IL-1β in the serum and reduce neuroinflammation." (PMID 36370154, 2023). "Furthermore, we detected pronounced IL-1β expression in active lesions of NMO patients, but not in stage-matched lesions of multiple sclerosis (MS) patients." (PMID 24252536, 2013).